PDPN (podoplanin)
Diseases named in the same sentence as PDPN in open-access papers (continued):
Sharing a sentence is not in itself a finding about the gene and the disease.
lymph node metastasis (40 papers, 2008 to 2025). "Podoplanin expression is significantly associated with histological grade (P=0.03) and lymph node metastasis (P=0.01)." (PMID 36247509, 2022). "There was a significant association between high podoplanin expression and poor histological grade (P=0.03) and the presence of lymph node metastasis (P=0.01)." (PMID 36247509, 2022). "Podoplanin is a recent marker strongly associated with lymph node metastasis, aggressive tumor behavior, and poor prognosis." (PMID 36247509, 2022). "In head and neck squamous cell carcinoma, overexpression of podoplanin is associated with lymph node metastasis and poor clinical outcome." (PMID 32993581, 2020). "PDPN expression in CAFs is thought to be correlated with poor prognosis and associated with lymph node metastasis and reduced OS in many malignancies." (PMID 32326079, 2020). "In PDAC, PDPN expression was associated with larger tumours 36, and was relevant for prognosis only in large tumours with lymph node metastasis 37, which themselves are adverse prognostic features." (PMID 30575030, 2019). "Podoplanin expression in stromal fibroblasts is associated with the poor prognosis of patients with large tumors or lymph node metastases of pancreatic cancer." (PMID 28702871, 2018). "PDPN expression in cancer-related fibrotic tissues is associated with a poor prognosis, especially in patients with large tumors or lymph node metastases." (PMID 28702871, 2018). "The number of lymphatic vessels highlighted by podoplanin expression was associated with lymph node metastasis." (PMID 26622791, 2015). "Several studies have shown that the presence of podoplanin is associated with lymph node metastasis of cancer cells and with poor prognosis." (PMID 24797369, 2014). "Additionally, it has been shown that tissue expressions of certain biomarkers, such as Cytokeratin, Podoplanin, Vimentin, Programmed Cell Death Ligand-1, or Epidermal Growth Factor Receptor, are significantly associated with the risk of lymph node metastasis." (PMID 37373623, 2023). "Podoplanin was associated with a fivefold rise in lymph node metastasis." (PMID 36247509, 2022). "Similarly, the presence of podoplanin-positive CAFs correlated with lymph node metastasis in patients with perihilar cholangiocarcinoma, and podoplanin expression in these CAFs was associated with increased migratory abilities." (PMID 30736372, 2019). "Thus, in squamous cell carcinoma of the uterine cervix, low levels of podoplanin were significantly associated with the presence of lymphatic invasion and lymph node metastasis, as well as with shorter survival and higher risk of tumour recurrence." (PMID 20196862, 2010). "Hence, podoplanin was associated with a fivefold increase in lymph node metastasis." (PMID 36247509, 2022). "Moreover, the podoplanin expression was significantly associated with lymph node metastasis (pN+)." (PMID 29310601, 2018). "Increased expression of podoplanin may cause a higher rate of lymph node metastasis." (PMID 24551781, 2012). "In univariate analysis, lymphovascular invasion (LVI) (P=0.01) and podoplanin expression (P=0.01) were significant predictors of lymph node metastasis." (PMID 36247509, 2022). "In our multivariable analysis, LVI and podoplanin expression were independent significant predictors of lymph node metastasis." (PMID 36247509, 2022). "In logistic regression analysis, podoplanin expression (Odds Ratio: 5.66, Confidence Interval: 1.23 -25.87, P=0.02) was a significant independent predictor of lymph node metastasis." (PMID 36247509, 2022). "LVI and podoplanin expression were significant predictors of lymph node metastasis in our univariable analysis." (PMID 36247509, 2022). "Our study demonstrates that podoplanin provides prognostic information and predicts lymph node metastasis which was consistent with our studies in the literature." (PMID 36247509, 2022).
lymph node metastasis (continued). "Similar to thrombocytosis, higher expression of podoplanin (PDPN) has been suggested as a predictive marker for higher frequency of lymph node metastasis of OSCC." (PMID 34987523, 2021). "Similar to high platelet counts, elevated PDPN expression was often found at the invasive front and correlated with lymph node metastasis in OSCC patients." (PMID 34987523, 2021). "The presence of podoplanin-positive CAFs was also found in synchronous lymph-node metastasis produced by HER2-positive metastatic breast carcinomas." (PMID 30736372, 2019). "Increased podoplanin has been shown to depict increased lymphatic vessel density indicative of lymph node metastasis." (PMID 27280700, 2016). "A number of studies have reported that podoplanin expression is correlated with lymph node metastasis, disease stage, lymphatic and vascular invasion, recurrence and a poor prognosis in ESCC." (PMID 26095281, 2015). "It was previously demonstrated that podoplanin expression predicts the progression of lymph node metastasis." (PMID 26622791, 2015). "Multivariate analysis demonstrated that strong podoplanin expression (HR, 3.084; 95% CI, 1.543–6.164) and lymph node metastasis (HR, 6.132; 95% CI, 2.355–15.916) were independent predictors of mortality in ESCC." (PMID 26095281, 2015). "Conversely, current several reports demonstrate that a lower expression level of podoplanin in cancer cells significantly correlated with a poor prognosis and a higher incidence of lymph node metastasis in both lung and cervical SCCs." (PMID 21034514, 2010). "PNI and podoplanin are independent predictors of lymph node metastasis and poor survival." (PMID 36247509, 2022). "In most cancers, the prognostic value of podoplanin expression in CAFs for patient outcome is negative, associated with lymph node metastasis and shorter overall survival." (PMID 30736372, 2019). "For example, the stromal podoplanin and carbonic anhydrase IX (CA IX) which were associated with lymph node metastasis in EAC did not make the same impact on ESCC." (PMID 26822225, 2016). "Therefore, the present study investigated the association of podoplanin with the VEGF-C/VEGFR-3 axia and the progression of lymph node metastasis." (PMID 26622791, 2015). "From these results, it may be hypothesized that podoplanin is a useful marker for predicting lymph node metastasis, but is of less value for predicting the progression of lymph node metastasis." (PMID 26622791, 2015). "PDPN loss of positivity in stromal cells was associated with presence of lymph node metastasis in one but not in another study." (PMID 24229053, 2013). "In addition, patients with lymph node metastasis and increased podoplanin expressions had shorter disease-specific survival rate than other patients." (PMID 24551781, 2012). "In addition, patients with lymph node metastasis and upregulated podoplanin expression had shorter disease-specific survival rate than other patients." (PMID 24551781, 2012). "In consistence, the expression of CAFs markers, like α-SMA, CD10, podoplanin and FSP1, is correlated with lymph node metastasis in the submucosal invasive CRC, therefore may allow for stratification of patients with high risk of lymph node metastasis." (PMID 34660589, 2021). "Lymph node metastasis in patients with squamous cell carcinoma is correlated with IGF2BP3 and PDPN expression." (PMID 36237306, 2022). "Significant variables in univariate analysis were used in multivariate logistic regression analysis, and it was observed that podoplanin (P=0.02) and LVI (P=0.01) were significant independent predictors of lymph node metastasis." (PMID 36247509, 2022). "Except for periostin, the lymphatic endothelium marker podoplanin expressed in CAFs correlated with the EAC lymphovascular invasion and lymph node metastasis." (PMID 26822225, 2016).
lymph node metastasis (continued). "Their findings revealed that PDPN expression did not correlate with lymphatic or venous invasion, lymph node metastasis, αSMA, PDGFR-β, and type-I collagen expression." (PMID 39451200, 2024). "Compared to those without metastasis, both circITGB6 and PDPN mRNA showed higher expression in samples with lymph node metastasis (cohort 2)." (PMID 37898647, 2023). "The positive and negative predictive values of podoplanin were determined concerning the presence or absence of lymph node metastasis." (PMID 36247509, 2022). "Many reports suggest that podoplanin promotes tumor and metastasis; however, there are several controversial reports that podoplanin expression in lung SCC correlates with lower incidence of lymph node metastasis and good prognosis." (PMID 28674748, 2017). "The genes of three markers of lymphatic endothelial commitment and development (PDPN, LYVE-1 and SLP-76) were significantly overexpressed in tissues of MIBC patients showing positive lymphovascular invasion (LVI+), lymph node metastasis (Ln+) and tumor progression." (PMID 28423532, 2017). "Podoplanin is frequently expressed in cutaneous head and neck squamous cell carcinoma (HNSCC) and may serve as predictor for regional lymph node metastasis, locoregional recurrence, and clinical outcome." (PMID 24551781, 2012). "The aim of this study was to determine the expression of markers such as the HER family, E-cadherin, and Podoplanin in a consecutive series of locally advanced CSCC of the trunk and extremities and to define clinical, pathological, and molecular factors related to lymph node metastasis and survival." (PMID 21773035, 2011). "NF-κB expression in tumor cells was significantly correlated with lymph node metastasis (χ2 = 32.727, P = 0.001), LVD (χ2 = 4.312, P = 0.038), VEGF-C expression (χ2 = 4.241, P = 0.039), podoplanin expression (χ2 = 8.076, P = 0.004), and Notch1 expression (χ2 = 9.675, P = 0.002)." (PMID 21939555, 2011). "However, podoplanin expression did not exhibit a significant correlation with the progression of lymph node metastasis." (PMID 26622791, 2015). "Taking into account that lymph node metastases in patients aged ≥45 correlates with unfavorable prognosis, our observation of high frequency of PDPN expression in tumor samples of these patients may imply the potential role of podoplanin in metastatic tendency of papillary thyroid carcinoma." (PMID 24797369, 2014).
lung carcinoma (37 papers, 2009 to 2025). "Of note PDPN positive fibroblasts are associated with poorer prognosis in some tumours such as lung cancers." (PMID 39619326, 2024). "Podoplanin (PDPN) is a commonly used CAF marker implicated in the invasiveness of lung cancer cells." (PMID 39403603, 2024). "Podoplanin (PDPN) expression in cancer‐associated fibroblasts (CAFs) (CAF‐PDPN) is considered a poor prognostic factor in nonsmall cell lung cancer, but little is known about its clinical significance in high‐grade neuroendocrine carcinoma of the lung (HGNEC)." (PMID 39487962, 2024). "Upregulation of PDPN has been observed in a variety of human cancers, including brain cancer, breast cancer, lung cancer, and mesothelioma, which is associated with poor prognosis." (PMID 34987523, 2021). "PDPN expression is associated with aggressive phenotypes of human cancer and is a poor prognostic marker in thyroid, esophageal, oral, and lung cancers." (PMID 29100400, 2017). "In this study, to elucidate the mechanism underlying the role of podoplanin in tumour progression, we knocked out or ectopically expressed podoplanin in lung cancer cells." (PMID 28642617, 2017). "In a collagen invasion assay involving co-cultured cancer cells and CAFs, PDPN+ CAFs created invasion tracks for lung cancer cells, and knockdown of PDPN in CAFs decreased invasion of both CAFs and cancer cells." (PMID 39780187, 2025). "As previously noted, CAFs that express PDPN in lung cancer patients have been found to be resistant to EGFR/TKI drugs, such as Gefitinib, and are associated with poor outcomes." (PMID 39403603, 2024). "A meta-analysis conducted on tumor-infiltrating PDPN+ fibroblasts showed that the overall survival of lung cancer patients decreased significantly with an increase in the recruitment of PDPN-positive fibroblasts." (PMID 39403603, 2024). "The results showed that IGF2BP3 positively regulated PDPN mRNA and protein levels in lung cancer cells." (PMID 37898647, 2023). "(2015) suggested that ezrin exerted a vital role in the invasion of lung cancer within PDPN‐expressing CAF‐composed TME." (PMID 36156321, 2023). "In PDPN-positive CAFs from lung tumors, the CAFs promote lung cancer cell resistance to inhibitors of EGFR." (PMID 37894446, 2023). "A potentially clinicallysignificant marker of CAF is the transmembrane mucin-likeprotein podoplanin (PDPN); to date, PDPN has beendescribed as a marker of lymphoid capillary progenitor cellsand CAFs in lung cancers." (PMID 35342854, 2022). "After full-text review, 7 eligible studies including 519 LUSC patients were selected out for meta-analysis of PDPN expression with OS of lung cancer patients." (PMID 32408907, 2020). "PDPN-positive fibroblast infiltration significantly decreased overall survival, disease-free survival, and progression-free survival in lung cancer patients." (PMID 31321241, 2019). "Intelectin-1 was expressed in only 1 of 88 cases of lung cancer, whereas calretinin, CK 5/6, podoplanin, and mesothelin were expressed in about 23%, 44%, 14%, and 40% of lung cancers, respectively." (PMID 22768319, 2012). "Co-HP binding to CLEC-2 blocked the interaction between CLEC-2 and PDPN in lung cancer." (PMID 38504248, 2024). "Although PDPN-positive CAFs are an independent marker for recurrence and short survival, the presence of CD204-positive TAMs along with PDPN overexpressing CAFs is another marker associated with a high risk of recurrence in lung cancer patients." (PMID 39403603, 2024). "Moreover, PDPN-positive fibroblasts recruited to the tumor microenvironment are also a poor prognostic marker for lung cancer patients." (PMID 39403603, 2024). "An in vivo experiment was conducted in a lung cancer animal model by co-injecting cancer cells with two types of human fibroblasts (vascular adventitial or lung tissue-derived fibroblasts) transfected with a vector expressing PDPN." (PMID 39403603, 2024).
lung carcinoma (continued). "Moreover, enhanced PDPN mRNA stability was also observed in BrM cells, suggesting that circITGB6/PDPN pathway participates in brain metastasis of lung cancer." (PMID 37898647, 2023). "Moreover, the activated circITGB6/IGF2BP3/PDPN axis is closely correlated to metastasis status in lung cancer patients, increased lymph node metastasis as well as worse prognosis in CRC patients, reinforcing the critical role of circITGB6 in tumor metastasis." (PMID 37898647, 2023). "Podoplanin expression in CAFs was recently proposed as a new biomarker and has been identified in various malignancies, including breast and lung cancers, and there is evidence of the involvement of TME in ENE development in the nodal microenvironment of oral cancers." (PMID 35256682, 2022). "Oksana Kowalczuk’s study also manifested that PDPN transcriptional downregulation was more significant in high-graded tumors (G3 or G4) compared with low-graded ones (G1 or G2) (P = 0.049) among I-III lung cancer patients, which coincides with our results." (PMID 32408907, 2020). "We hope to emphasize the possibility that EGFR-TKIs and/or suppressing PMPA could be effective for the PDPN-positive lung cancers and bladder carcinomas." (PMID 28642617, 2017). "Moreover, we cut serial sections of lung cancer tissue, and stained them with podoplanin, CD31 and VEGFR-3, respectively." (PMID 19216806, 2009). "NZ-12 may be used for the treatment of PDPN-expressing brain cancer and lung cancer." (PMID 38504248, 2024). "Primary human LFs were stably transfected with short-hairpin (sh) RNA plasmid against podoplanin (shPDPN) or control vector (shCON), and their effects on CSC formation and tumorigenesis of lung cancer cells were examined." (PMID 27996035, 2016). "The responses of lung cancers with podoplanin-positive CAFs to EGFR tyrosine kinase inhibitors (TKIs) are worse than those of lung cancers with podoplanin-negative CAFs." (PMID 32171304, 2020). "Interestingly, TGF-β blockade significantly inhibits podoplanin-induced EMT and metastasis in mice injected with highly metastatic lung cancer cells, suggesting that podoplanin mediates tumor metastasis by mounting platelet-derived TGF-β." (PMID 30791448, 2019). "To further investigate the role of CNT-induced CAF-like cells in the tumor formation of lung cancer cells and to develop a potential predictive biomarker for CNT carcinogenicity, we evaluated the functional role of podoplanin in the tumor-promoting effect of CNT-induced CAF-like cells." (PMID 27996035, 2016). "However, in both vivo and vitro in lung cancer, Hanako Suzuki revealed that exogenous PDPN had no influence on tumor growth, and PDPN significantly restrained axillary lymph node metastasis associated with the suppression of lymphangiogenesis through the downregulation of EBC-1-derived VEGF-C mRNAs." (PMID 32408907, 2020).